ENSG00000291313 (novel protein)
Gene: Protein-coding gene on chromosome 14 (103,334,237 to 103,335,932, forward strand). Ensembl gene ENSG00000291313.
Homologues: Orthologues: mouse Gm58608 (98% identical).